CFTR (CF transmembrane conductance regulator)
Diseases named in the same sentence as CFTR in open-access papers (continued):
Sharing a sentence is not in itself a finding about the gene and the disease.
cystic fibrosis (continued). "Collectively, these findings show that CFTR modulators can restore critical aspects of cystic fibrosis pancreatic epithelial physiology in vitro, even under pro-inflammatory stress, supporting their potential relevance beyond the airway disease." (PMID 40868962, 2025). "Mutations in the CFTR gene, which encodes a chloride channel essential for electrolyte and fluid transport in organs such as the colon, pancreas, lungs, and sweat glands, cause cystic fibrosis, a classic autosomal recessive disorder." (PMID 41614802, 2025). "The Cystic Fibrosis Foundation recommends the inclusion of a CFTR sequencing tier following IRT and CFTR variant panel testing to improve the specificity and positive predictive value of CF newborn screening." (PMID 40265445, 2025). "Molecular-targeted therapies for the treatment of cysticfibrosis rely on small-molecule modulators that rescue the activity ofthe defective CF transmembrane conductance regulator (CFTR) anionchannel." (PMID 39928576, 2025). "In conclusion, while CFTR modulators have marked a new era in cystic fibrosis care, their full implications extend far beyond lung function." (PMID 41154689, 2025). "The range in sample size with lower number of samples for chenodeoxycholic acid and deoxycholic acid was attributed to the interfering of the BA with CFTR-potentiators e.g., Ivacaftor, given to patients with Cystic Fibrosis." (PMID 41310203, 2025). "CFTR-associated diseases include cystic fibrosis and CFTR-related diseases (CFTR-RD)." (PMID 40332394, 2025). "People with cystic fibrosis variants that exhibit residual function (RF) of the CF transmembrane conductance regulator are considered to have a milder disease; however, the spectrum of CF phenotype within the different RF variants has not been extensively investigated." (PMID 39811546, 2025). "As a result of CFTR modulators, cystic fibrosis is becoming an increasingly prevalent disease in adults who face new nutritional challenges, including obesity." (PMID 41380738, 2025). "Genetically modified mouse models with specific alterations in CFTR have been developed to study the pathophysiology of cystic fibrosis." (PMID 40869482, 2025). "Ivacaftor is an essential component of triple combination CFTR modulator therapy for pharmacological restoration of F508del-CFTR function and mucociliary clearance in cystic fibrosis airways." (PMID 40261705, 2025). "Baroni and colleagues used SAXS to evaluate the conformation of the cystic fibrosis transmembrane conductance regulator (CFTR), a membrane-integral chloride channel, whose mutations are responsible for the onset of cystic fibrosis." (PMID 40733051, 2025). "Cystic fibrosis is a hereditary disorder caused by mutations in the CFTR (cystic fibrosis transmembrane conductance regulator) gene, which encodes a chloride and bicarbonate channel crucial for maintaining the balance of ion and water transport across epithelial surfaces." (PMID 40066329, 2025). "The current focus is improving lung-targeted delivery using optimized vectors and nanoparticles to achieve lasting CFTR correction with minimal immune response (First inhaled lentiviral gene therapy enters cystic fibrosis trial, 2025)." (PMID 41416220, 2025). "AE remains a valuable option for haemoptysis control in cystic fibrosis, with outcomes further improved following initiation of CFTR modulators." (PMID 41439858, 2025). "The cystic fibrosis transmembrane conductance regulator (CFTR) is an epithelial Cl− channel, defective in the genetic disease cystic fibrosis." (PMID 40154618, 2025). "Cystic fibrosis, a disease caused by mutations in the cystic fibrosis transmembrane conductance regulator (CFTR) gene, which encodes the cystic fibrosis transmembrane conductance regulator, shows promising insights through recent studies." (PMID 40321594, 2025). "Our study aimed to investigate the infection rates of P. aeruginosa during CFTR modulator therapy in patients with cystic fibrosis." (PMID 40700326, 2025).
cystic fibrosis (continued). "As an example, cystic fibrosis is a genetic disorder caused by mutations in the CFTR gene, which impairs secretion of fluid across the cell membrane and leads to the production of thick and sticky mucus that builds up and causes severe respiratory and digestive issues." (PMID 40772719, 2025). "CF is caused by mutations in the cystic fibrosis transmembrane conductance regulator (CFTR) gene on chromosome 7, resulting in folding defects of the CFTR protein, an ATP-binding cassette transmembrane chloride channel located in the apical membranes of epithelial cells." (PMID 40890826, 2025). "We have previously discovered that the new leading treatment in cystic fibrosis, CFTR modulators Elexacaftor/Tezacaftor/Ivacaftor (ETI, Trikafta), drastically reduces the colonization and infection by Aspergillus fumigatus." (PMID 40736245, 2025). "CF is an autosomal recessive disorder caused by mutations in the cystic fibrosis transmembrane conductance regulator (CFTR) gene, which results in dysfunctional CFTR channels." (PMID 41436524, 2025). "Cystic fibrosis transmembrane conductance regulator protein (CFTR) modulators have significantly improved health outcomes in patients with cystic fibrosis (pwCF)." (PMID 41158800, 2025). "The introduction of CFTR modulators in the clinics has improved body mass index in cystic fibrosis individuals." (PMID 40076690, 2025). "Cystic fibrosis is a multisystem, autosomal recessive genetic disorder caused by mutations or variants in the CF transmembrane conductance regulator (CFTR) gene that encodes an anion channel that controls the movement of chloride, bicarbonate, and water across the epithelium." (PMID 40720490, 2025). "The CFTR protein is present in a variety of epithelial cells, as well as innate and adaptive immune cells, hence the multi-system nature of cystic fibrosis affecting the lungs, gastrointestinal tract, pancreas, liver, and reproductive tract." (PMID 40137248, 2025). "Cystic fibrosis is the most prevalent autosomal recessive genetic condition in patients of European descent and is caused by mutations in the cystic fibrosis transmembrane conductance regulator (CFTR) protein." (PMID 40430241, 2025). "This large, multi-national retrospective cohort study compared clinical outcomes, hospitalization rates, and survival between children and adolescents with cystic fibrosis who received CFTR modulator therapies." (PMID 40003259, 2025). "Since the advent of cystic fibrosis transmembrane conductance regulator (CFTR) modulators, the quality of life of cystic fibrosis patients has improved dramatically." (PMID 40276963, 2025). "The advent of highly effective Cystic Fibrosis Transmembrane conductance Regulator (CFTR)-modulator therapy (HEMT) for people with Cystic Fibrosis (pwCF) has dramatically improved the lives and prognosis of eligible pwCF." (PMID 40979741, 2025). "Symdeko, a cystic fibrosis transmembrane conductance regulator (CFTR), is widely utilized for treating cystic fibrosis." (PMID 41244782, 2025). "CFTR gene modulators have been shown to exert beneficial effects in individuals with cystic fibrosis." (PMID 41009994, 2025). "Ivacaftor was the first CFTR potentiator that expressed clinically significant improvements in lung function and nutritional status in patients with cystic fibrosis." (PMID 40700326, 2025). "We also note that additional long-term data in participants with cystic fibrosis are being collected in the open-label extension study of this trial to demonstrate the clinical benefits and safety of even greater CFTR function restoration." (PMID 39756425, 2025). "Recent studies have shown that CFTR modulators, particularly ETI, are associated with increased gut microbiota diversity in individuals diagnosed with cystic fibrosis." (PMID 41009994, 2025).
cystic fibrosis (continued). "Advancements in cystic fibrosis treatment, particularly with highly‐effective CF transmembrane conductance regulator (CFTR) modulator therapies (HEMT), have greatly improved the life prospects of many people with CF (pwCF)." (PMID 40071679, 2025). "Restoring normal CFTR function early in life has the potential to prevent manifestations of cystic fibrosis." (PMID 39756425, 2025). "The cystic fibrosis transmembrane conductance regulator (CFTR) is dysregulated in multiple respiratory diseases including cystic fibrosis and chronic obstructive pulmonary disease and has proven a valuable therapeutic target." (PMID 39358991, 2025). "The high variety of mutations found in the Cystic Fibrosis Transmembrane Regulator (CFTR) gene is responsible for the clinical heterogeneity observed in people with Cystic Fibrosis and the atypical manifestations in CFTR-related disorders (CFTR-RD)." (PMID 40301948, 2025). "The measurement of sweat chloride concentration, a method developed in 1959, is considered the gold-standard clinical marker for evaluating CFTR function and confirms the diagnosis of cystic fibrosis in 98 % of cases." (PMID 40553696, 2025). "Cystic fibrosis transmembrane conductance regulator (CFTR) modulator therapy has significantly changed the course of the disease in people with cystic fibrosis (pwCF)." (PMID 40202901, 2025). "Longitudinal profiling of the cystic fibrosis airway epithelium reveals partially reduced inflammation, infection, and normalization of epithelial function in response to CFTR modulator therapy." (PMID 41212059, 2025). "This study aimed to investigate the infection rates of P. aeruginosa during CFTR modulator therapy in patients with cystic fibrosis." (PMID 40700326, 2025). "The motivation for studying miRNA therapeutics for CFTR upregulation in cystic fibrosis is based on the fact that CFTR correctors and modulators are beneficial for about 80% of the patients with cystic fibrosis." (PMID 39846681, 2025). "Cystic fibrosis patients suffer from increased lung and airway mucus because of a dysfunctional cystic fibrosis transmembrane conductance regulator (CFTR)." (PMID 41114581, 2025). "Cystic fibrosis is an autosomal recessive genetic disorder caused by mutations in the cystic fibrosis transmembrane conductance regulator (CFTR) gene, located on chromosome 7, which regulates the transport of chloride and bicarbonate ions across epithelial membranes." (PMID 40361862, 2025). "Fibrosis transmembrane conductance regulator (CFTR) modulators (CFTRms) have significantly improved outcomes in people with cystic fibrosis." (PMID 40507740, 2025). "Cystic fibrosis is a genetic disease hallmarked by a defective cystic fibrosis transmembrane conductance regulator (CFTR) protein that results in severe multi-organ disease manifestations with particularly damaging effects for the lung." (PMID 40972653, 2025). "Induced fit has also been proposed to explain the gating mechanisms of the cystic fibrosis transmembrane conductance regulator (CFTR)." (PMID 40831506, 2025). "Cystic fibrosis is an autosomal recessive condition that affects the CF transmembrane conductance regulator (CFTR)." (PMID 40144821, 2025). "WGS also incidentally identified compound heterozygosity for two pathogenic variants in CFTR, supporting an incidental cystic fibrosis diagnosis, clinically verified by an abnormal sweat test and radiological findings of subclinical bronchiectasis, as the child was asymptomatic." (PMID 40861057, 2025). "Cystic Fibrosis is a genetic disorder affecting ~100,000 patients worldwide that is caused by mutations that impair the expression and/ or function a chloride channel known as the Cystic Fibrosis Transmembrane Conductance Regulator (CFTR)." (PMID 40964320, 2025). "Small molecules that enhance CFTR folding (correctors) or activity (potentiators) have advanced to the clinic for cystic fibrosis treatment." (PMID 40750590, 2025).
cystic fibrosis (continued). "Thirty years later, an AAV vector was used to deliver the cystic fibrosis transmembrane regulator (CFTR) gene packaged with the AAV2 capsid (rAAV2-CFTR), into a patient with cystic fibrosis." (PMID 39516652, 2025). "Cystic fibrosis is a multi-system disease caused by CFTR dysfunction." (PMID 41318507, 2025). "Cystic Fibrosis Screen Positive Inconclusive Diagnosis/CFTR-related Metabolic Syndrome (CFSPID/CRMS) presents a significant clinical challenge due to its variable diagnostic outcomes and uncertain disease progression." (PMID 40700044, 2025). "KB-R7943 treatment improved survival and reduced P. aeruginosa bacterial burden in mice with cystic fibrosis transmembrane conductance regulator (CFTR) knockout, demonstrating efficacy in cystic fibrosis-specific lung infection." (PMID 41367495, 2025). "Eligible participants were aged 6–11 years with at least one elexacaftor–tezacaftor–ivacaftor-responsive CFTR variant, FEV1 % predicted of 60% or higher, and stable cystic fibrosis as determined by investigators." (PMID 39756425, 2025). "In combination with CFTR channel activators like ivacaftor, these pharmacological chaperones markedly reduce respiratory symptoms and hospitalizations in patients with cystic fibrosis." (PMID 41026531, 2025). "The goal of cystic fibrosis transmembrane conductance regulator (CFTR) modulators is to reach normal CFTR function in people with cystic fibrosis." (PMID 39756424, 2025). "Cystic fibrosis is a multisystemic autosomal recessive disorder caused by mutations in the cystic fibrosis transmembrane conductance regulator (CFTR) gene, resulting in dysfunctional CFTR protein expression and impaired epithelial chloride and bicarbonate transport." (PMID 41006969, 2025). "In Poland, since 1 April 2025, CFTR modulators Kaftrio + Kalydeco (ivacaftor + tezacaftor + elexacaftor and ivacaftor) have been used as drugs for cystic fibrosis patients from 2 years of age." (PMID 40364218, 2025). "Cystic fibrosis is an autosomal recessive disease caused by a mutation in the gene on the long arm of chromosome 7 that encodes the CFTR (Cystic Fibrosis Transmembrane Conductance Regulator) protein involved in the passage of chloride ion across cell membranes." (PMID 40647163, 2025). "An AbbVie medicinal chemistry team had identified a promising series of trisubstituted cyclopropanes during a drug discovery campaign focused on developing CFTR C2 correctors for the treatment of cystic fibrosis." (PMID 41256986, 2025). "The 2017 consensus guidelines for CF diagnosis from the Cystic Fibrosis Foundation recommend sweat chloride testing and CFTR genetic analysis to establish the diagnosis of CF." (PMID 40128832, 2025). "In summary, current evidence indicates that CFTR modulators hold potential to positively affect glucose metabolism in cystic fibrosis, particularly when introduced before significant pancreatic β-cell loss occurs." (PMID 41332894, 2025). "Overall, vanzacaftor–tezacaftor–deutivacaftor had a similar effect on lung function as elexacaftor–tezacaftor–ivacaftor, with the potential to result in greater improvements in CFTR function in a broader population of people with cystic fibrosis." (PMID 39756424, 2025). "Cystic fibrosis is an autosomal recessive disease caused by sequence variants involving the CF transmembrane conductance regulator (CFTR) gene, resulting in reduced function of the CFTR protein anion channel present in different epithelial linings." (PMID 41226552, 2025). "Cystic fibrosis transmembrane conductance regulator (CFTR), the membrane channel involved in the pathogenesis of cystic fibrosis, was downregulated following Streptococcus pneumoniae infection." (PMID 38686182, 2024). "Ivacaftor is the first potentiator of the cystic fibrosis transmembrane conductance regulator (CFTR) protein approved for use alone in the treatment of cystic fibrosis." (PMID 39329117, 2024).
cystic fibrosis (continued). "CFTR regulates cystic fibrosis transmembrane transduction, which mainly regulates cell water content by activating the chloride pathway, whereas EGFR can also cause intestinal edema by inhibiting cell growth." (PMID 39597698, 2024). "Loss-of-function mutations of the CFTR gene cause the life-shortening genetic disease cystic fibrosis, whereas overactivity of CFTR may lead to secretory diarrhea and polycystic kidney disease." (PMID 39107303, 2024). "The highly effective cystic fibrosis transmembrane conductance regulator (CFTR) modulator, elexacaftor–tezacaftor–ivacaftor, is now widely being used by people with cystic fibrosis." (PMID 38935410, 2024). "Class 2, the most common among those with cystic fibrosis, accounting for 88%, can produce CFTR protein, but the protein is misfolded, which disrupts its transfer to the cell surface, known as a trafficking defect." (PMID 39583120, 2024). "Mutations in the CFTR gene cause cystic fibrosis, a recessive genetic disorder." (PMID 38666024, 2024). "The approval of the cystic fibrosis transmembrane conductance regulator (CFTR) modulator triple therapy elexacaftor/tezacaftor/ivacaftor (ETI) in 2019 was a breakthrough in the treatment of people with cystic fibrosis (pwCF)." (PMID 38956524, 2024). "Cystic fibrosis is caused by mutations in the CFtransmembraneconductance regulator (CFTR) protein." (PMID 38527911, 2024). "In August 2020, a triple combination of CFTR modulators, containing elexacaftor, tezacaftor, and ivacaftor (ETI), was licensed in the EU to treat people living with cystic fibrosis (pwCF) with at least one F508del mutation." (PMID 39452571, 2024). "In the lung, ionocytes express the ion channel CFTR, frequently mutated in individuals with cystic fibrosis and FOXI1 loss significantly decreases expression of CFTR in the mouse airway epithelium and leads to cystic fibrosis-like phenotypes." (PMID 39324331, 2024). "In summary, the development and approval of CFTR modulator therapy has substantially changed the patient landscape in cystic fibrosis." (PMID 39595943, 2024). "What is more, the use of an AAV2 vector carrying CFTR cDNA led to a great improvement in FEV1 in cystic fibrosis patients." (PMID 39199292, 2024). "The dysfunction of cystic fibrosis transmembrane conductance regulator (CFTR) gene contributes to abnormal HE4 expression via NF-κB in cystic fibrosis." (PMID 38304432, 2024). "More recently, CFTR modulating agents have been shown to reduce AP episode frequency and improve pancreatic exocrine function among individuals with cystic fibrosis." (PMID 39172977, 2024). "CF is an autosomal recessive life-limiting illness caused by a defect in the cystic fibrosis transmembrane conductance regulator (CFTR) protein encoded by the CFTR gene." (PMID 38877530, 2024). "The implementation of cystic fibrosis transmembrane conductance regulator (CFTR) modulator drugs into clinical practice has been attaining remarkable therapeutic outcomes for CF, a life-threatening autosomal recessive genetic disease." (PMID 38248793, 2024). "Cystic fibrosis is caused by mutations in the cystic fibrosis transmembrane conductance regulator (CFTR) gene, which results in altered chloride and bicarbonate secretion and the accumulation of abnormally thick mucus in the lungs and intestine, affecting more than 70,000 people worldwide." (PMID 39081882, 2024). "Arteriovenous metabolomics in newborn cystic fibrosis pigs reveals an intrinsic role of the CFTR anion channel in controlling multiorgan metabolism." (PMID 38743489, 2024). "SUMOylation of the cystic fibrosis transmembrane conductance regulator (CFTR) involves its degradation and is a potential therapeutic target in the treatment of cystic fibrosis." (PMID 39697538, 2024). "The first phase 1 clinical trial of AdV-based gene therapy in 1996 delivered the cystic fibrosis transmembrane conductance regulator (CFTR) gene to patients with cystic fibrosis." (PMID 39044426, 2024).